GOLGA5 (golgin A5)
Description:
Involved in maintaining Golgi structure. Stimulates the formation of Golgi stacks and ribbons. Involved in intra-Golgi retrograde transport.
Synonyms: RFG5; ret-II; golgin-84; GOLIM5
Tractability: Antibody: UniProt predicts a signal peptide or a membrane-spanning region. PROTAC: ubiquitination databases record sites on it; its protein half-life has been measured.
Gene: Protein-coding gene on chromosome 14 (92,794,230 to 92,839,963, forward strand). Ensembl gene ENSG00000066455.
Subcellular location: Golgi apparatus membrane
Subcellular location (Human Protein Atlas): Golgi apparatus
Pathways (Reactome):
Vesicle-mediated transport: Intra-Golgi traffic
Gene Ontology:
Molecular function: protein homodimerization activity; small GTPase binding; protein-macromolecule adaptor activity
Biological process: Golgi organization; Golgi vesicle transport; retrograde transport, vesicle recycling within Golgi
Cellular component: cis-Golgi network; Golgi apparatus; Golgi cisterna; membrane; Golgi membrane; transport vesicle
Genetic constraint (gnomAD): Loss-of-function variants: 25 observed, 46.01 expected, observed/expected ratio (o/e) 0.54, 90% interval 0.4 to 0.76. The upper end of that interval is the gene's LOEUF score, 0.76, which puts it in group 3 of 6, group 1 being the genes least tolerant of losing a copy. Missense variants: 466 observed, 554.4 expected, observed/expected ratio (o/e) 0.84, 90% interval 0.78 to 0.91. Synonymous variants: 222 observed, 214.38 expected, observed/expected ratio (o/e) 1.04, 90% interval 0.93 to 1.16.
Homologues: Orthologues: macaque GOLGA5 (97% identical), dog GOLGA5 (91% identical), guinea pig GOLGA5 (88% identical), chimpanzee GOLGA5 (86% identical), pig GOLGA5 (85% identical), rat Golga5 (85% identical), mouse Golga5 (84% identical), rabbit GOLGA5 (69% identical), tropical clawed frog golga5 (68% identical), zebrafish golga5 (59% identical), Drosophila melanogaster Golgin84 (21% identical), Caenorhabditis elegans golg-5 (20% identical).
Diseases named in the same sentence as GOLGA5 in open-access papers:
GOLGA5 is named in the same sentence as 8 diseases in open-access papers, as found by Europe PMC text mining. Sharing a sentence is not in itself a finding about the gene and the disease. The quoted sentences say what the papers report.
papillary thyroid carcinomas (1 paper, 2022). "GOLGA5 is a RET proto-oncogene interacting gene; its gene fusion pattern is characteristic of patients with papillary thyroid carcinomas who were exposed at young age to radioiodine released from the Chernobyl reactor." (PMID 36088851, 2022).
spindle cell sarcoma (1 paper, 2022). A malignant mesenchymal neoplasm composed of spindle-shaped cells. "Additionally, in our cohort, selpercatinib was administered to a patient with spindle cell sarcoma harboring a GOLGA5-RET gene fusion." (PMID 36088851, 2022). "Additionally, 1 spindle cell sarcoma case harbored GOLGA5-RET fusion." (PMID 36088851, 2022).
infection (6 papers, 2011 to 2021). The state of being infected such as from the introduction of a foreign agent such as serum, vaccine, antigenic substance or organism. "In our study, JNK inhibitor could disturb GM130 polar distribution, and SAPK/JNK siRNA infection could also decrease the expression of Golga2 and Golga5 mRNA." (PMID 33770099, 2021).
cancer (3 papers, 2020 to 2025). A tumor composed of atypical neoplastic, often pleomorphic cells that invade other tissues. "For HPV-associated SNSCC with matched normal DNA the most frequently mutated COSMIC cancer driver genes included KMT2D (4/12 patients, 33%), FGFR3 and KMT2C (3/12 patients, 25%), GOLGA5, TET1, and ARID1B (2/12 patients, 16.7%)." (PMID 40500270, 2025). "Known cancer genes such as COL1A1 or STK11 were affected by duplications and other known genes such as CDKN2A, JAK2, PRDM1, FBXW7, or GOLGA5 were affected by deletions in several tumors of this subcluster." (PMID 32604718, 2020).
GOLGA5 also shares sentences with these, for which no sentence is quoted: Chlamydia infection (2 papers); chlamydial infection (2); lysosomal storage disease (1); osteosarcoma (1).